ADGRL2 (adhesion G protein-coupled receptor L2)
Description:
Orphan adhesion G protein-coupled receptor (aGPCR), which mediates synapse specificity (By similarity). Ligand binding causes a conformation change that triggers signaling via guanine nucleotide-binding proteins (G proteins) and modulates the activity of downstream effectors (By similarity). Following G protein-coupled receptor activation, associates with cell adhesion molecules that are expressed at the surface of adjacent cells to direct synapse specificity. Specifically mediates the establishment of perforant-path synapses on CA1-region pyramidal neurons in the hippocampus. Localizes to postsynaptic spines in excitatory synapses in the S.lacunosum-moleculare and interacts with presynaptic cell adhesion molecules, such as teneurins, promoting synapse formation (By similarity).
Synonyms: KIAA0786; LEC1; LPHH1; LPHN2; CIRL2; CL2
Tractability: Antibody: UniProt places it where antibodies can reach, with medium confidence; UniProt predicts a signal peptide or a membrane-spanning region; its Gene Ontology location is reachable by antibodies, with medium confidence; the Human Protein Atlas places it where antibodies can reach. PROTAC: its protein half-life has been measured.
Gene: Protein-coding gene on chromosome 1 (81,306,112 to 81,993,940, forward strand). Ensembl gene ENSG00000117114.
Subcellular location: Postsynaptic cell membrane
Subcellular location (Human Protein Atlas): Plasma membrane
Gene Ontology:
Molecular function: G protein-coupled receptor activity; latrotoxin receptor activity; carbohydrate binding; transmembrane signaling receptor activity
Biological process: excitatory synapse assembly; G protein-coupled receptor signaling pathway; cell surface receptor signaling pathway
Cellular component: membrane; plasma membrane; postsynaptic membrane
Genetic constraint (gnomAD): Loss-of-function variants: 26 observed, 120.02 expected, observed/expected ratio (o/e) 0.22, 90% interval 0.16 to 0.3. The upper end of that interval is the gene's LOEUF score, 0.3, which puts it in group 1 of 6, group 1 being the genes least tolerant of losing a copy. Missense variants: 1,313 observed, 1,606.7 expected, observed/expected ratio (o/e) 0.82, 90% interval 0.78 to 0.86. Synonymous variants: 500 observed, 577.82 expected, observed/expected ratio (o/e) 0.87, 90% interval 0.8 to 0.93.
Homologues: Orthologues: chimpanzee ADGRL2 (99% identical), macaque ADGRL2 (99% identical), rabbit ADGRL2 (98% identical), pig ADGRL2 (98% identical), dog ADGRL2 (97% identical), guinea pig ADGRL2 (96% identical), mouse Adgrl2 (96% identical), rat Adgrl2 (94% identical), tropical clawed frog adgrl2 (90% identical), zebrafish adgrl2a (75% identical), zebrafish ADGRL2 (67% identical), zebrafish adgrl2b.1 (26% identical). Paralogues in human: ADGRL1 (65% identical), ADGRL3 (59% identical), ADGRL4 (17% identical), ADGRE5 (16% identical), ADGRB1 (15% identical), ADGRE2 (15% identical), ADGRB2 (14% identical), ADGRE3 (14% identical), ADGRD1 (13% identical), ADGRE1 (13% identical), ADGRG6 (13% identical), ADGRB3 (13% identical), and 30 more.
Diseases named in the same sentence as ADGRL2 in open-access papers:
ADGRL2 is named in the same sentence as 59 diseases in open-access papers, as found by Europe PMC text mining. Sharing a sentence is not in itself a finding about the gene and the disease. The quoted sentences say what the papers report.
breast carcinoma (6 papers, 2012 to 2024). "ADGRL2, also called LPHH1, PLHN1, and LPHN2 is a G-protein coupled receptor that triggers exocytosis from neurons and neuroendocrine cells It had previously been found to be variably expressed in breast cancer cell lines and silenced by epigenetic modifications in human gastric and colon cancers." (PMID 33919687, 2021).
gastric cancer (4 papers, 2019 to 2022). A primary or metastatic malignant neoplasm involving the stomach. "The Human Protein Atlas shows that high ADGRL2 expression is considered an unfavorable prognostic marker in endometrial cancer, stomach cancer, and liver cancer." (PMID 33919687, 2021). "Recent research has shown the low expression level of ADGRL2 in genomic sequencing analyses of both gastric cancer and colon cancer cell lines due to the hypermethylation of CpG islands within the gene." (PMID 31921812, 2019). "Hypomethylated ADGRL2 (LPHN2) and GTSE1 are potential biomarkers of cisplatin-sensitive gastric cancer." (PMID 35309131, 2022).
depression (3 papers, 2021 to 2024). "While it may be premature to draw conclusions about the role of ADGRL2 in migraine with accompanying depression, the 26 different polymorphisms associated with ADGRL2 show that the gene might represent an important novel target of migraine research." (PMID 34972135, 2021). "Furthermore, results allowed the separation of variants that play a role in migraine accompanied by depression, like ADGRL2, REST and HPSE2, from those that play a general role in migraine, like PRDM16." (PMID 34972135, 2021). "In summary, interaction analysis indicated that intergenic rs12128399, rs6660757 and variants in HPSE2, REST and from the 1p31.1 region (including ADGRL2) represent lifetime depression-dependent genetic factors for migraine." (PMID 34972135, 2021). "While the p31.1 region and PRDM16 are worthy of further investigations in migraine in general, REST, HPSE2 and ADGRL2 may be prime candidates behind migraine pathophysiology in patients with comorbid depression." (PMID 34972135, 2021). "Furthermore, this study also provides evidence that SNPs of the previously identified migraine risk genes REST, ADGRL2, HPSE2 and 1p31.1 show lifetime depression-dependent associations with the disease." (PMID 34972135, 2021). "Bayesian relevance analysis confirmed the relevance of intergenic rs6660757 and rs12128399 (p31.1), rs1043215 (REST), rs1889974 (HPSE2) and rs11163394 (ADGRL2) from depression interaction results, and the moderate relevance of rs77864828 and rs2455107 of PRDM16 from main effect analysis." (PMID 34972135, 2021). "In contrast, intergenic rs6660757 and rs12128399, rs1889974 in HPSE2, rs11163394 in ADGRL2 and rs1043215 of REST may only serve as biomarkers in migraine accompanied by lifetime depression." (PMID 34972135, 2021).
glioma (3 papers, 2010 to 2020). A benign or malignant brain and spinal cord tumor that arises from glial cells (astrocytes, oligodendrocytes, ependymal cells). "Significantly recurrent focal deletions were present in a novel putative glioma driver Adgrl2 (GISTIC q value = 2.19 × 10−6)." (PMID 32727536, 2020). "Recurrent deletions in previously unknown glioma genes NT5C2, ADGRL2, and UIMC1 were observed whilst SUB1, CES1, and ITGA6 were frequently methylated in human LGGs; frequent CNVs in these genes were also present in human GBMs." (PMID 32727536, 2020).
microcephaly (3 papers, 2018 to 2022). A congenital or acquired developmental disorder in which the circumference of the head is smaller than normal for the person's age and sex. "In a study examining a deleterious de novo ADGRL2 variant associated with microcephaly, ADGRL2 was found to be expressed early during embryonic development; according to the ExAC consortium, the ADGRL2 gene is loss-of-function intolerant (pLI = 1)." (PMID 33919687, 2021). "ADGRL2 is the first gene identified as being responsible for extreme microcephaly with rhombencephalosynapsis." (PMID 30340542, 2018). "In Adgrl2+/− mice, MRI studies revealed microcephaly and vermis hypoplasia." (PMID 30340542, 2018). "Also due to normal proliferative indices, extreme microcephaly with no sulcation associated with this ADGRL2 variant is unlikely to be connected to mitotic spindle dysfunction." (PMID 30340542, 2018). "We report for the first time the association of extreme microcephaly with almost no sulcation and rhombencephalosynapsis in a fœtus for which comparative patient-parent exome sequencing strategy revealed a heterozygous de novo missense variant in the ADGRL2 gene." (PMID 30340542, 2018).
diabetes (2 papers, 2023 to 2025). "In the context of diabetes, ADGRL2 may influence insulin signaling pathways, adipogenesis, and inflammation, which are critical in glucose homeostasis." (PMID 39941463, 2025).
migraine (2 papers, 2021 to 2024). "In summary, analyses presented in this paper validate polymorphisms in p31.1 region of chromosome 1, PRDM16, ADGRL2, REST and HPSE2 genes in migraine." (PMID 34972135, 2021).
schizophrenia (2 papers, 2017 to 2019). A major psychotic disorder characterized by abnormalities in the perception or expression of reality. "Recently, a single nucleotide variation in an intronic sequence of the ADGRL2 gene was reported in patients diagnosed with schizophrenia who were prescribed clozapine, an antipsychotic usually recommended for the treatment of schizophrenia." (PMID 31354411, 2019). "The network analysis of the 7 annotated genes revealed 5 networks, each with PARK2, N4BP2, KCNIP4, ADGRL2, or NCOA7 as its focus gene, which may have joint influence on the initiation of schizophrenia." (PMID 28744025, 2017).
brain malformation (1 paper, 2022). "Secondly, the ADGRL2 (LPHN2) gene was previously associated with a mild brain malformation (rhombencephalosynapsis)." (PMID 35887345, 2022).
diabetic nephropathy (1 paper, 2018). "Increased expression levels were found for ADGRL2, ADGRL4, ADGRE1, ADGRE5, ADGRG2, and ADGRG6 in lupus nephritis and diabetic nephropathy, whereby ADGRL2, ADGRL4 and ADGRE5 were also upregulated in IgA nephropathy." (PMID 29468160, 2018).
endothelial dysfunction (1 paper, 2024). In vascular diseases, endothelial dysfunction is a systemic pathological state of the endothelium (the inner lining of blood vessels) and can be broadly defined as an imbalance between vasodilating and vasoconstricting substances produced by (or acting on) the endothelium. "The major findings of the present study are the protective functions of ADGRL2 in endotoxemia-induced endothelial dysfunction, including increased eNOS activity and upregulation of antioxidative defense systems." (PMID 39594576, 2024).
Hypertension (1 paper, 2024). The presence of chronic increased pressure in the systemic arterial system. "The Cardiovascular Disease Knowledge Portal reported four SNPs near the 5’ end of the ADGRL2 gene that exhibit genome-wide association with hypertension." (PMID 38886581, 2024).
infarction (1 paper, 2023). A localised pathological necrosis of tissue resulting from obstruction of the blood supply usually by a thrombus, an embolus, or vascular torsion. "Previous reports have suggested that ADGRL2 is a marker for heart development and induces myocardial repair after infarction." (PMID 37097149, 2023).
Insulin resistance (1 paper, 2025). Increased resistance towards insulin, that is, diminished effectiveness of insulin in reducing blood glucose levels. "The dysregulation of ADGRL2 signaling could contribute to insulin resistance and the development of T2DM." (PMID 39941463, 2025).
lung squamous cell carcinoma (1 paper, 2019). "ADGRL2 is also associated with lung squamous cell carcinoma and may serve as the diagnostic marker for small cell lung cancer." (PMID 31921812, 2019).
malaria (1 paper, 2018). Malaria is a serious and sometimes fatal disease caused by a parasite that commonly infects a certain type of mosquito which feeds on humans. "Likewise, although significant associations were seen between severe malaria and polymorphisms in seven additional genes (IL10, LPHN2 [ADGRL2], LOC727982, ARL14, RPS6KL1, CAND1, and GNAS), without further data their potential for translation remains elusive." (PMID 30033078, 2018).
Sepsis (1 paper, 2024). Sepsis is defined as life-threatening organ dysfunction caused by a dysregulated host response to infection. "An increase in the ADGRL2 levels improves endothelial functionality, and this aGPCR could therefore be a promising therapeutic target for the treatment of sepsis to protect the endothelium and, thus, to restore endothelial cell integrity." (PMID 39594576, 2024).
tuberculosis (1 paper, 2024). A chronic, recurrent infection caused by the bacterium Mycobacterium tuberculosis. "The results of ROC showed that TYMP (AUC = 0.964), LAP3 (AUC = 0.914), ADGRL2 (AUC = 0.98), SIL1 (AUC = 0.936), LMO7 (AUC = 0.856), SULF1 (AUC = 0.96), ANXA3 (AUC = 0.798), and PACSIN3 (AUC = 0.747) had high accuracy in predicting tuberculosis." (PMID 39023413, 2024).
cancer (11 papers, 2011 to 2026). A tumor composed of atypical neoplastic, often pleomorphic cells that invade other tissues. "Those with ADGRL2 variants were slightly more likely to be diagnosed with UC compared to a non-cancer control cohort matched for age, sex, and smoking status." (PMID 33919687, 2021). "As the fold change threshold increased (>3.0), the number of differentially expressed genes decreased, but core regulatory genes such as ADGRL2, NR2F1, S100A16, and KRT19 remained consistently altered, highlighting isoform-specific regulation of key cancer-associated genes." (PMID 41300774, 2025). "We found a number of genes involved in G protein-coupled receptor signaling (ARAP2, LPHN2, LPHN3, EPHA4, ADGRL2, and GPC5) consistent with observations in pan-cancer studies." (PMID 35538064, 2022).
tumor (8 papers, 2014 to 2024). "Assuming a genotypic model of inheritance, genetic markers in the LPHN2 (also known as ADGRL2) and GRIK1 genes explained much of the variability in tumor response (14% and 10.4% respectively) in our data." (PMID 29290962, 2017).
infection (4 papers, 2014 to 2024). The state of being infected such as from the introduction of a foreign agent such as serum, vaccine, antigenic substance or organism. "This work provides better insight into cell-surface AnxA2 and ADGRL2, which upregulate Src and p38MAPK signaling pathways to enhance ARV entry and productive infection." (PMID 37097149, 2023).
Cardiovascular Disease (1 paper, 2024). "Human genetic data reveal a correlation between the latrophilin-2-encoding Adgrl2 gene and cardiovascular disease." (PMID 38886581, 2024).
ADGRL2 also shares sentences with these, for which no sentence is quoted: colon cancer (3 papers); acute monocytic leukemia (1); acute myeloid leukemia (1); Allergy (1); Anxiety (1); asthma (1); autoimmune disease (1); autoimmune disorders (1); breast tumors (1); colorectal cancer (1); common variable immunodeficiency (1); emphysema (1); Encephalocele (1); endometrial cancer (1); endotoxemia (1); ependymoma (1); heart failure (1); holoprosencephaly (1); Hyperglycemia (1); IgA nephropathy (1); ischemic stroke (1); liver cancer (1); lung carcinoma (1); lupus nephritis (1); male infertility (1); melanoma (1); ovarian carcinoma (1); prostate carcinoma (1); rectum adenocarcinoma (1); rhombencephalosynapsis (1).
A further 7 diseases each share a sentence with ADGRL2 in 1 paper.